CSPG4 (chondroitin sulfate proteoglycan 4)
Diseases named in the same sentence as CSPG4 in open-access papers (continued):
Sharing a sentence is not in itself a finding about the gene and the disease.
melanoma (continued). "Previous studies showed the inhibition of CSPG4+ melanoma cells in vitro and in vivo with this agent and reported that antitumoural activity was enhanced in the presence of the sigma receptor (σR) rimcazole, also known to have selective antitumoural activity." (PMID 24969320, 2014). "Chondroitin sulfate proteoglycan 4 (CSPG4) is a promising target antigen that is overexpressed in multiple cancer histologies including melanoma, triple-negative breast cancer, glioblastoma, mesothelioma and sarcoma." (PMID 25197555, 2014). "This suggested that xenogeneic electrovaccination against CSPG4 is able to overcome host unresponsiveness to the “self” antigen and seems to be effective in treating canine malignant melanoma." (PMID 25506617, 2014). "The three CARs that demonstrated surface expression on PBL also demonstrated IFN-γ release when cocultured with the CSPG4-expressing melanoma lines mel1300 and mel888." (PMID 25197555, 2014). "Studies have demonstrated the effectiveness of targeting CSPG4 with monoclonal antibody (mAb)-based immunotherapy, both in vitro and in mouse models, to treat melanoma, triple-negative breast cancer, and mesothelioma." (PMID 25197555, 2014). "When peripheral blood mononuclear cells (PMBCs) from healthy donors co-cultured with melanoma cells were treated with MCSP-BiTE antibodies at different doses, PBMCs lysed CSPG4-expressing melanoma cells in an antigen-specific manner." (PMID 24969320, 2014). "In this assay the relative CSPG4 antigen expression in three melanoma samples was 4.668, 9.665, and 24.041." (PMID 25197555, 2014). "Dogs with stage II-III surgically resected CSPG4-positive oral malignant melanoma were subjected to monthly intramuscular plasmid administration, which was followed immediately by electroporation (electrovaccination) from 6 to 20 months." (PMID 25506617, 2014). "Immunohistochemistry was utilized to assay resected melanomas and normal human tissues (n = 30) for CSPG4 expression and a reverse-phase protein array comprising 94 normal tissue samples was also interrogated for CSPG4 expression." (PMID 25197555, 2014). "Like MCAM, CSPG4 is widely expressed on melanoma cells, appearing on >85% of cutaneous melanoma lesions and melanoma cell lines." (PMID 24069584, 2013). "Transfection of CSPG4 stimulated melanoma cell motility in a scratch wound assay, an effect believed to be indicative of metastatic potential." (PMID 24069584, 2013). "On melanoma, it is predominately chondroitin sulfate carried by CSPG4 that binds and activates the SG-1 site." (PMID 24069584, 2013). "Inhibition of CSPG4 expression by siRNA in melanoma cells expressing endogenous CSPG4 reduced Erk1,2 activation and anchorage dependent growth." (PMID 24069584, 2013). "MCAM, CSPG4, and Gal-3 are associated with angiogenesis and CSPG4 is involved with the activation of pro-MMP-2 on melanoma (relevant references are in the review)." (PMID 24069584, 2013). "Involvement of PAX3 in melanoma migration is further supported by evidence showing that other genes associated with cell migration, including MCAM, CSPG4, and CXCR4, are targeted by PAX3, as shown by ChIP assay in A2058 melanoma cells." (PMID 24069584, 2013). "A number of reports have indicated that CSPG4 expression enhances the proliferation of melanoma cells in vitro and in vivo." (PMID 24069584, 2013). "The level of CSPG4 expression is similar between lentigo maligna, nodular, and superficial spreading melanoma lesions but it is lower in primary acral lentiginous melanoma lesions." (PMID 24069584, 2013). "CSPG4 expression levels clearly separate conjuctival melanoma from conjuctival nevi and in one study lower CSPG4 expression appeared to be correlated with increased risk of recurrence." (PMID 24069584, 2013). "The gene, CSPG4, encoding the NG2 or human melanoma proteoglycan, is turned off upon terminal differentiation, but is aberrantly re-expressed by several tumor types." (PMID 24127551, 2013).
melanoma (continued). "Collectively these studies provide convincing evidence that CSPG4 is a useful biomarker for melanoma." (PMID 24069584, 2013). "Chondroitin sulfate proteoglycan 4 (CSPG4) was first identified over three decades ago as a surface antigen on human melanoma cells." (PMID 24069584, 2013). "CSPG4 was first identified in human melanoma as a melanoma specific antigen and has been evaluated as a target for melanoma therapy." (PMID 22984505, 2012). "We previously reported that CSPG4 plays a key role in promoting spreading, migration, invasion, as well as growth of malignant human melanoma cells." (PMID 22984505, 2012). "Recent studies suggest that CSPG4 plays a key role in maintaining stem cell phenotypes in various tumor types such as melanoma, glioblastoma, and breast cancer cells." (PMID 22984505, 2012). "In order to confirm that P-selectin binds to CSPG4 we used CSPG4-transfected M14 melanoma cell line available in the lab." (PMID 21658254, 2011). "In support of work done in melanoma and recent studies in breast cancer, the studies outlined here strongly suggest that CSPG4 can be an available target for immunotherapy of breast cancer." (PMID 21658254, 2011). "Specifically, chondroitin sulfate proteoglycan 4, a cell surface proteoglycan is known to regulated in the adhesion, migration and invasion of tumor cells such as human melanoma and infantile acute myeloid leukemia." (PMID 19812696, 2009). "Melanoma-associated antigens have been used to generate vaccines able of evoking an immune response against canine OMM, specifically tyrosinase and chondroitin sulfate proteoglycan 4 (CSPG4)." (PMID 40786979, 2025). "Additionally, CSPG4‐specific chimeric antigen receptors (CARs) exerted potent cytotoxicity in response to various CSPG4‐expressing tumors, such as melanoma, breast cancer, mesothelioma, glioblastoma, and osteosarcoma, in animal models and in vitro." (PMID 40700516, 2025). "To date, CSPG4 expression had only been investigated in primary and metastasized melanoma tissues." (PMID 40700516, 2025). "CSPG4-targeting CAR-Ms exhibited specific phagocytosis of CSPG4-expressing melanoma cells." (PMID 40082557, 2025). "This study assessed CSPG4 expression in benign nevi (BN), dysplastic nevi (DN), and superficial spreading melanomas (SSM), comparing it with PRAME (PReferentially expressed Antigen in MElanoma) and evaluating the cell division cycle 7‐related protein kinase (CDC7) and the proliferation marker Ki67." (PMID 40700516, 2025). "We used the human metastatic melanoma cell line A375 to test whether CSPG4-targeting CAR-Ms phagocytose melanoma cells." (PMID 40082557, 2025). "CSPG4 was first discovered in 1981 to be overexpressed on malignant melanoma cells." (PMID 41375047, 2025). "We reasoned that the CAR-Ms did not need to stay in the tumor for the entirety of the experiment, but CAR-Ms must be present in the tumor long enough to phagocytose CSPG4-positive melanoma cells and potentially reprogram the tumor environment for a sustained response." (PMID 40082557, 2025). "To determine whether CAR-macrophages (CAR-Ms) specifically target and kill melanoma cells, we engineered CAR-Ms targeting chondroitin sulfate proteoglycan 4 (CSPG4), an antigen expressed in melanoma." (PMID 40082557, 2025). "A high percentage of oral canine melanomas express the CSPG4 antigen." (PMID 40284831, 2025). "Here, we describe the known functions of CSPG4 in healthy states and in melanoma." (PMID 39409881, 2024). "CSPG4 is selectively up regulated in melanoma, is essential to melanoma growth, and has been identified as a target for chimeric antigen receptor T cell therapy for individuals with melanoma." (PMID 39137780, 2024). "CSPG4 is essential to melanoma growth and may even represent a therapeutic target for treatment of melanoma." (PMID 39137780, 2024).
melanoma (continued). "One study details a decline of T-helper cell reactivity against CSPG4 in melanoma patients compared with healthy subjects, suggesting that there may be potential CSPG4-specific protection against melanoma cells in non-malignant states." (PMID 39409881, 2024). "We review different antibody-based and immunotherapeutic approaches targeting CSPG4 in melanoma and discuss how such immune cell-targeting interventions could be refined to attain, enhance, prolong, or maintain clinical efficacy." (PMID 39409881, 2024). "Similarly, CSPG4/MCSP has been described as a marker for circulating melanoma cells and EV marker for malignant melanoma." (PMID 38353833, 2024). "Another CSPG4 targeting murine IgG2a antibody, clone 9.2.27, which recognizes a distinct and spatially distant epitope of human CSPG4, was evaluated as a potential treatment against a human melanoma cell line." (PMID 39409881, 2024). "Anti-CSPG4 TCRs have shown T cell recognition of CSPG4-expressing melanoma cell lines." (PMID 39409881, 2024). "Furthermore, anti-CSPG4 IgE significantly prolonged the survival of patient-derived melanoma xenografts engrafted with autologous patient immune cells, showcasing the potency of CSPG4-specific IgE mAbs against CSPG4-expressing patient-derived melanomas." (PMID 39409881, 2024). "Alternatively, combining CSPG4-CAR T cells with conventional treatments for melanoma, like BRAF and MEK inhibitors (BRAFi/MEKi), may provide a further treatment strategy." (PMID 39409881, 2024). "In addition, the involvement of CSPG4 in the adhesion and motility of melanoma cells on FN1 substrates has been reported." (PMID 38338902, 2024). "This hypothesis, however, was not tested by evaluating the cytotoxicity of those CAR T cells towards healthy, non-melanoma CSPG4-expressing cells." (PMID 39409881, 2024). "Moreover, Chondroitin Sulfate Proteoglycan 4 (CSPG4) exhibits increased expression in various cancers, including melanoma, breast cancer, and renal cell carcinoma, positioning it as a potential target for antitumor immunotherapy." (PMID 38961326, 2024). "Nevertheless, these early studies show that vaccines inducing a humoral response against CSPG4 could hold promise for the treatment of melanoma, with longstanding effects, minimal toxicities and limited development of resistance." (PMID 39409881, 2024). "In addition to impact on CSPG4 expression, treatment of the mouse melanomas with exogenous ARSB increased the activity of SHP2, attributable to less binding of SHP2 with C4S following ARSB, as previously." (PMID 37813168, 2024). "Alternatively, CSPG4-CAR T cells produced through mRNA electroporation rather than viral transduction, a technique which reduces toxicity through temporary restriction of CAR expression, resulted in cytokine secretion and successful lysing of CSPG4-positive melanoma cells." (PMID 39409881, 2024). "Similarly, CSPG4 expression was also shown to confer resistance of melanoma cells to TNFα, doxorubicin and cisplatin treatment, most likely through activation of α3β1 integrin/PI3K signalling, which promotes cell survival." (PMID 39409881, 2024). "Another recent study analysed CSPG4 protein expression by immunohistochemistry in melanoma samples (n = 428) and normal tissues (n = 558) and found expression in a similar proportion of melanomas (63%), a finding recapitulated by transcriptomic analyses." (PMID 39409881, 2024). "Regulation of CSPG4 by this pathway could be relevant to the up regulation of the gene in melanoma cells." (PMID 39137780, 2024). "We review different approaches designed to activate the patient’s immune system to target CSPG4-expressing melanomas, and we discuss how such interventions could be translated into clinical practice." (PMID 39409881, 2024). "However, in the more recent study, CAR T cells produced pro-inflammatory cytokines and exhibited cytotoxic activity when co-cultured with CSPG4-expressing melanoma cells in vitro." (PMID 39409881, 2024).
melanoma (continued). "In addition, soluble CSPG4 has been detected in the serum of both healthy individuals and melanoma patients." (PMID 39409881, 2024). "Moreover, transfer of anti-CSPG4 chimeric-antigen receptor (CAR)-T cells eradicated established melanomas in mice." (PMID 37849763, 2023). "Of note CSPG4-reactive CD4+ T cells have been identified in melanoma patients before." (PMID 37849763, 2023). "Here we aimed to evaluate these functions in the context of CSPG4 IgE and melanoma." (PMID 37185332, 2023). "Efficacy of CSPG4 IgE was superior to CSPG4 IgG in the subcutaneous human melanoma model." (PMID 37185332, 2023). "In this context, it is encouraging that CD4+ T cell-mediated anti-CSPG4 responses have been detected in both healthy individuals and melanoma patients, and that both CD8+ T-cell clones described herein were retrieved from the peripheral blood of a melanoma patient." (PMID 37849763, 2023). "Our findings support CSPG4 as a valuable target for CAR CIK-based immunotherapy in melanoma." (PMID 37993874, 2023). "That way, exosomes expressing CSPG4 were considered melanoma-derived exosomes." (PMID 37022605, 2023). "CSPG4 IgE conferred Fc-mediated functions in vitro in the presence of high and intermediate CSPG4-expressing melanoma cells: ADCC mediated by human effector cells, including monocytes from healthy individuals and patients with melanoma; and RBL-SX38 cell degranulation." (PMID 37185332, 2023). "The HLA-C*07:01 allele is highly prevalent and CSPG4 represents an optimal immunotherapeutic target due to its consistent upregulation in melanoma, and low/absent expression in healthy tissue." (PMID 37849763, 2023). "The biological relevance of CSPG4 in several crucial tumor processes, like tumorigenesis/stemness, aggressiveness and metastatic spread has been reported in melanoma and other cancer settings, further valuing the potential interest of its targeting for clinical applications." (PMID 37993874, 2023). "Next, we co-cultured the T-cell clones with either 293T cells transfected with HLA-C*07:01 or HLA-C*07:02 cDNA and loaded with the CSPG4:554-562 (9-mer) or CSPG4:553-562 (10-mer) peptide or cotransfected with CSPG4:1-562 cDNA or co-cultured them with HLA-C*07:02+CSPG4+ melanoma cell lines." (PMID 37849763, 2023). "Our findings support CSPG4 as a valuable CAR target in melanoma and provide translational rationale for clinical studies exploring CAR-CIK cellular immunotherapies within the challenging setting of patients not responsive or relapsing to immune checkpoint inhibitors." (PMID 37993874, 2023). "It was previously reported that high expression of CSPG4 and its downstream signaling pathways in melanoma cells may contribute to tumor progression." (PMID 37185332, 2023). "Moreover, in melanoma CSPG4 modifies the NF-κB pathway to promote tumour angiogenesis, and CS groups present on CSPG4 have been shown to act as ligands for P-selectin, a cell adhesion molecule on the surface of activated endothelial cells." (PMID 36428658, 2022). "Interestingly, CSPG4 is also highly expressed at multiple stages of melanoma, even in pre-malignant naevi." (PMID 36428658, 2022). "In accordance with the results in our study involving ovarian cancer cells, CSPG4-positivity could be induced in more than 50% of decitabine-treated melanoma cells." (PMID 36291817, 2022). "Anti-CSPG4 antibodies induced by the vaccination directly down-regulate CSPG4 expression in-vitro hampering CSPG4 tumorigenic functions in melanoma cells, suggesting that they could have a beneficial impact on the clinical course of the disease." (PMID 35224082, 2022). "However, while CSPG4′s potential as a drug target and marker has been explored in other malignancies, such as melanoma, there has been less focus on CSPG4 as a putative biomarker and therapeutic target in aggressive SCCs." (PMID 36428658, 2022).
melanoma (continued). "We recently showed the good-prognosis value of high CSPG4 expression in a series of 309 GIST, whereas higher expression was associated with poorer prognosis in melanoma, glioblastoma, breast cancer, head and neck squamous cell carcinomas, and hepatocellular carcinoma." (PMID 36221119, 2022). "However, further investigation of the link between CSPG4 expression and patient response to (immune) therapy in melanoma remains largely unexplored." (PMID 36428658, 2022). "Decline in ARSB leads to reduced binding of galectin-3 with C4S and increased availability of galectin-3 for nuclear translocation and cooperation with AP-1 and Sp1 in promoter activation, for expression of genes such as Wnt9A in colonic epithelium, versican in prostate cells, and CSPG4 in melanoma." (PMID 36361933, 2022). "CSPG4, the receptor for TcdB, is abundantly expressed in cancers including over 70% of melanomas." (PMID 35324891, 2022). "The bispecific antibody PD-L1xCSPG4 may improve the selectivity, effectiveness and safety of the therapies against malignant tumors overexpressing CSPG4, including melanoma." (PMID 35401191, 2022). "A CSPG4-coated magnetic bead can capture CSPG4+ exosomes produced by melanoma cells." (PMID 36051582, 2022). "Both Con-IgE and Neu-IgE recognized and bound the target antigen CSPG4-expressing A2058 human melanoma cells in a similar dose-dependent manner, suggesting that sialic acid reduction had no obvious impact on the Fab-mediated binding of IgE on target antigen-expressing cancer cells." (PMID 36362241, 2022). "CSPG4 plays a crucial role in melanoma cell proliferation, migration, invasion, and metastasis." (PMID 34207884, 2021). "We found that the anti-CSPG4 IgE and IgG antibodies in their conjugated forms could bind to CSPG4-overexpressing A375 melanoma cells and to Fc receptor-expressing immune cells." (PMID 34513315, 2021). "Regarding A-1155463, while it did not affect melanoma cell viability, it increased the effect of immunotoxin targeting the melanoma-associated chondroitin sulfate proteoglycan 4 (CSPG4) when combined with the Mcl-1 specific inhibitor, S63845." (PMID 33803452, 2021). "CSPG4 is overexpressed in various cancers including melanoma in dogs and human patients." (PMID 35053051, 2021). "Moreover, CSPG4, a highly immunogenic cell surface proteoglycan identified on melanoma cells, has been shown to facilitate the progression from radial to vertical growth in melanoma tumours." (PMID 34585512, 2021). "Indeed, the proteoglycan glypican-1 (GPC1) and the tumor antigen chondroitin sulfate proteoglycan 4 (CSPG4) were detected in tumor exosomes from heterogeneous samples of pancreatic cancer or melanoma, respectively." (PMID 33430152, 2021). "According to their data, in plasma of these patients they could also capture melanoma antigen CSPG4, indicating the presence of melanoma-derived EV at the systemic level, despite the early stage of disease." (PMID 34439311, 2021). "After capture using ferrofluid coupled with antibodies against melanoma cell adhesion molecule (MCAM), circulating melanoma cells are identified by staining with antibodies against high molecular weight melanoma-associated antigen (HMW-MAA), also known as CSPG4." (PMID 32984308, 2020). "Flow cytometry showed a specific binding to CSPG4 (+) melanoma cell lines." (PMID 33050185, 2020). "We therefore selected melanoma as a target tumor for an anti-CSPG4 ADC bearing a PDD payload." (PMID 32331483, 2020). "Extracted melanoma cells were treated with Anti-CSPG4-(PDD) ex vivo." (PMID 32331483, 2020). "Interestingly, melanoma cells harvested from the three mice that responded for 50 days after ADC treatment remained sensitive to anti-CSPG4-(PDD) treatment ex vivo compared with A375 tumor cells harvested from the isotype-(PDD) treatment mouse." (PMID 32331483, 2020).